PCED1A (PC-esterase domain containing 1A)
Synonyms: C20orf81; FAM113A; bA12M19.1; FLJ22376
Tractability: No criterion of Open Targets' tractability assessment is met for any kind of drug.
Gene: Protein-coding gene on chromosome 20 (2,835,314 to 2,841,190, reverse strand). Ensembl gene ENSG00000132635.
Subcellular location (Human Protein Atlas): Cytosol; Nucleoplasm
Gene Ontology:
Molecular function: protein binding
Genetic constraint (gnomAD): Loss-of-function variants: 20 observed, 41.94 expected, observed/expected ratio (o/e) 0.48, 90% interval 0.34 to 0.69. The upper end of that interval is the gene's LOEUF score, 0.69, which puts it in group 2 of 6, group 1 being the genes least tolerant of losing a copy. Missense variants: 497 observed, 614 expected, observed/expected ratio (o/e) 0.81, 90% interval 0.75 to 0.87. Synonymous variants: 236 observed, 247.97 expected, observed/expected ratio (o/e) 0.95, 90% interval 0.86 to 1.06.
Homologues: Orthologues: chimpanzee PCED1A (100% identical), macaque PCED1A (99% identical), dog PCED1A (92% identical), pig PCED1A (91% identical), guinea pig PCED1A (90% identical), mouse Pced1a (85% identical), rat Pced1a (85% identical), rabbit PCED1A (82% identical), zebrafish fam113 (38% identical), tropical clawed frog pced1a (36% identical), Caenorhabditis elegans D2030.8 (25% identical). Paralogues in human: PCED1B (50% identical).
Diseases named in the same sentence as PCED1A in open-access papers:
PCED1A is named in the same sentence as 4 diseases in open-access papers, as found by Europe PMC text mining. Sharing a sentence is not in itself a finding about the gene and the disease. The quoted sentences say what the papers report.
Obesity (2 papers, 2024 to 2025). Accumulation of substantial excess body fat. "Although research on PCED1A remains limited, emerging evidence suggests its involvement in fatty acid metabolism and obesity development." (PMID 40463370, 2025). "Gene prioritisation considering SNP GERP scores, variant consequences, and allele comparison with other mouse lines identified seven novel obesity candidate genes: 4930441H08Rik, Aff3, Fam237b, Gm36633, Pced1a, Tecrl, and Zfp536." (PMID 38483771, 2024).
breast carcinoma (1 paper, 2024). "In breast cancer datasets, the five most important mRNAs were GABARAP, PFDN5, RPL21, CFB, and PCED1A." (PMID 39495117, 2024).
tumor (1 paper, 2025). "The results showed that all genes exhibited significant differential expression in tumor tissues; however, only four genes (CAPS, DAPK1, P4HA1, and PCED1A) demonstrated independent prognostic value." (PMID 40463370, 2025).
PCED1A also shares sentences with these, for which no sentence is quoted: cancer (1 paper).